MSI1 (musashi RNA binding protein 1)
Description:
RNA binding protein that regulates the expression of target mRNAs at the translation level. Regulates expression of the NOTCH1 antagonist NUMB. Binds RNA containing the sequence 5'-GUUAGUUAGUUAGUU-3' and other sequences containing the pattern 5'-[GA]U(1-3)AGU-3'. May play a role in the proliferation and maintenance of stem cells in the central nervous system (By similarity).
Tractability: PROTAC: ubiquitination databases record sites on it; its protein half-life has been measured.
Gene: Protein-coding gene on chromosome 12 (120,341,329 to 120,369,437, reverse strand). Ensembl gene ENSG00000135097.
Subcellular location: Cytoplasm; Nucleus
Subcellular location (Human Protein Atlas): Cytosol; Nucleoplasm
Pathways (Reactome):
Developmental Biology: Regulation of expression of SLITs and ROBOs
Gene Ontology:
Molecular function: identical protein binding; protein binding; RNA binding; molecular condensate scaffold activity; nucleic acid binding; poly(U) RNA binding; protein homodimerization activity; single-stranded RNA binding
Biological process: central nervous system development; nervous system development; regulation of translation; epithelial cell differentiation; response to hormone
Cellular component: cytoplasm; nucleus
Genetic constraint (gnomAD): Loss-of-function variants: 15 observed, 44.12 expected, observed/expected ratio (o/e) 0.34, 90% interval 0.23 to 0.52. The upper end of that interval is the gene's LOEUF score, 0.52, which puts it in group 2 of 6, group 1 being the genes least tolerant of losing a copy. Missense variants: 304 observed, 449.56 expected, observed/expected ratio (o/e) 0.68, 90% interval 0.62 to 0.74. Synonymous variants: 200 observed, 178.51 expected, observed/expected ratio (o/e) 1.12, 90% interval 1 to 1.26.
Homologues: Orthologues: chimpanzee MSI1 (100% identical), dog MSI1 (100% identical), rat Msi1 (99% identical), mouse Msi1 (99% identical), macaque MSI1 (97% identical), guinea pig MSI1 (96% identical), pig MSI1 (92% identical), rabbit MSI1 (90% identical), tropical clawed frog msi1 (90% identical), zebrafish msi1b (74% identical). Paralogues in human: MSI2 (69% identical), DAZAP1 (33% identical), HNRNPA3 (32% identical), HNRNPD (30% identical), HNRNPDL (30% identical), HNRNPA1 (29% identical), HNRNPA2B1 (29% identical), HNRNPA1L2 (28% identical), HNRNPA1L3 (28% identical), HNRNPA0 (28% identical), HNRNPAB (28% identical), RBMX (25% identical), and 24 more.
Diseases named in the same sentence as MSI1 in open-access papers:
MSI1 is named in the same sentence as 123 diseases in open-access papers, as found by Europe PMC text mining. Sharing a sentence is not in itself a finding about the gene and the disease. The quoted sentences say what the papers report.
glioblastoma (54 papers, 2012 to 2025). The most malignant astrocytic tumor (WHO grade IV). "High Msi1 levels have been observed in multiple tumors including glioblastoma and are often associated with poor patient outcomes and tumor growth." (PMID 33804958, 2021). "For instance, both Msi1 and Msi2 have been implicated in colon cancer, but Msi1 and Msi2 have unique ties to glioblastoma and leukemia, respectively." (PMID 35011618, 2021). "Downregulation of MSI1 in glioblastoma cell lines caused prolongation of cell cycle through accumulation of cyclinB1." (PMID 32448364, 2020). "Following chemotherapy treatment in glioblastoma, enhancement of MSI1 expression causes IL-6 secretion through activation of AKT." (PMID 32448364, 2020). "In U251 glioblastoma cells, downregulation of Musashi-1 (MSI1) was associated with upregulation of TRPM8." (PMID 29221175, 2017). "Msi1 is a stem cell related RNA binding protein implicated in stem cell self-renewal and development of both medulloblastoma and glioblastoma." (PMID 24465609, 2014). "In addition, increased MSI1 expression was associated with the formation and rapid progression of different tumors, particularly glioblastoma." (PMID 38879014, 2024). "Additionally, Musashi-1 (MSI1) is a posttranscriptional gene expression regulator associated with high oncogenicity in glioblastoma that positively regulates the expression of YTHDF1." (PMID 35625706, 2022). "Ribonucleoprotein immunoprecipitation followed by microarray analysis (RIP-chip) indicated that Small GTP Binding Protein, Rac1, Connective Tissue Growth Factor (CTGF), and Syntenin are the major mRNA targets of an MSI1-associated network in U251 glioblastoma cells." (PMID 32448364, 2020). "The reduction of MSI1 in glioblastoma cells caused other abnormalities in cell-cycle regulation." (PMID 22428049, 2012). "In glioblastoma, Musashi-1 (MSI1), an RNA-binding protein, inhibited TNS3 translation by binding its mRNA 3’UTR, promoting migration." (PMID 40906372, 2025). "In glioblastoma, MSI1 directly interacts with the TNS3 mRNA 3’UTR to inhibit its translation, thereby activating RhoA and promoting migration." (PMID 40906372, 2025). "In glioblastoma, Lut binds Musashi-1 (MSI-1), inhibiting macrophage M2 polarization and attenuating pro-tumor functions." (PMID 41479912, 2025). "The overexpression of MSI1 has been observed in multiple malignancies, including glioblastoma, lung, breast, and colon cancer, and has been reported to promote tumor growth and recurrence." (PMID 38328550, 2024). "A recent report has implicated that MSI1 regulated the expression of m6A reader YTHDF1, thus involving glioblastoma cell proliferation and migration." (PMID 37675218, 2023). "In glioblastoma, overexpression of MSI1 modifies transcripts of checkpoint proteins to hyperactivate the DNA damage repair mechanism, which results in CSC-associated irradiation resistance." (PMID 37853437, 2023). "The expression of the RBP Musashi 1 (MSI1) can be repressed by a class of tumour suppressor miRNAs, including miR-34a, miR-138, and miR-137, inhibiting the proliferation of glioblastoma and medulloblastoma cells." (PMID 35062979, 2022). "Treatment failure in malignant tumors glioblastoma multiform (GBM) had also been correlated to CSC-regulating properties of MSI1." (PMID 35158774, 2022). "In our previous study, MSI1 acted as a glioblastoma stem-like cell marker and promoted tumor migration and radioresistance." (PMID 35052701, 2021). "In Msi1 KO glioblastoma cells, we observed that G1-S transition is disrupted, agreeing with an increase in expression of Msi1 targets p21 and p27 and downregulation of CDK2 and CCNE2." (PMID 33804958, 2021). "A comprehensive genomic analysis identified a network of cell cycle/division and DNA replication genes and established these processes as Msi1’s core regulatory functions in glioblastoma." (PMID 33804958, 2021).
glioblastoma (continued). "MSI1 equips cancer stem cells and enhances chemoresistance in glioblastoma cells via altering the PKR/eIF2 pathway and generating SGs." (PMID 35004322, 2021). "Previously, we observed a downregulation of E2Fs in Msi1 KO glioblastoma cells and established them as the main drivers of Msi1 impact on cell cycle/division genes." (PMID 35011618, 2021). "In this respect, we have previously observed synergistic effects when Msi1 inhibitor Luteolin was combined with radiation or Olaparib to treat glioblastoma cells." (PMID 33804958, 2021). "To establish Msi1’s main contributions to glioblastoma development, we analyzed U251 and U343 Msi1 knockout (KO) lines and their controls by RNA-seq and conducted then an integrated analysis, using Msi1 expression profiles and other genomic datasets." (PMID 33804958, 2021). "Currently, it has been reported that MSI1 depletion enhances the sensitivity of glioblastoma multiforme to radiation through weakening tumor invasion." (PMID 33882945, 2021). "To link changes in gene expression triggered by Msi1 KO to phenotypes, we conducted assays to measure alterations in the cell cycle, cell division, and DNA replication of glioblastoma cells." (PMID 33804958, 2021). "In view of the spreading of glioblastoma cancer stem cells into surrounding brain tissue escaping cancer therapy, MSI1 was shown to promote cell adhesion, migration and invasion." (PMID 34062997, 2021). "For example, in cellular models of glioblastoma, only the splicing of very few genes is controlled by Msi1." (PMID 34916907, 2021). "In this context, the formation of stress granules is suggested to be involved in MSI1–mediated chemoresistance in refractory glioblastoma." (PMID 34062997, 2021). "Consistent with our previous observations in glioblastoma, Msi1 silencing altered cell cycle progression, leading cells to arrest in the G1 phase." (PMID 35011618, 2021). "In this view, it was previously shown that MSI1 promotes cancer stem cell properties of glioblastoma cells via upregulation of the m6A reader YTHDF1 (YTH N6–methyladenosine RNA–binding protein 1)." (PMID 34062997, 2021). "MSI-1-mediated modulation of radiation resistance observed in the present study is in line with previous findings in glioblastoma, colon cancer, and our previous findings in MDA-MB-231 TNBC cells." (PMID 34291358, 2021). "By silencing HuR in U251 and U343 glioblastoma cell lines, the proliferation of cells is reduced and apoptosis is increased, but with ectopic expression of MSI1, apoptosis will be rescued." (PMID 32448364, 2020). "A previous study in glioblastoma demonstrated that MSI-1 knockdown resulted in lower expression of DNA-Protein Kinase catalytic subunit (DNA-PKcs), a key DNA repair protein, and, subsequently, increased radiosensitivity." (PMID 32245259, 2020). "Inhibition of MSI1 increased the efficiency of radiotherapy and the overexpression of MSI1 induced chemoresistance in glioblastoma." (PMID 32448364, 2020). "Tumor suppressor miRNAs (miR-34a, miR-101, miR-128, miR-137, and miR-138) regulate expression of MSI1 in U251 glioblastoma and Daoy medulloblastoma cells." (PMID 32448364, 2020). "The stem cell marker Musashi1 (MSI1) is highly expressed during neurogenesis and in glioblastoma (GBM)." (PMID 33291443, 2020). "MSI1 already represents a potential therapeutic target for the treatment of glioblastoma, as luteolin has been shown to inhibit the RNA-binding properties of MSI1 and disrupts cancer phenotypes in glioblastomas." (PMID 32408494, 2020). "Radiation research has so far identified MSI-1 as a marker of radioresistance in two tumor entities only, in glioblastoma and in colon cancer." (PMID 32245259, 2020). "Another previous study reported that diffuse spread of expression of MSI1 was observed during enhanced tumor cell proliferation in human glioblastoma and medulloblastoma cell lines." (PMID 31708751, 2019).
glioblastoma (continued). "A similar effect was seen for the RBP Musashi1 (MSI1), which is involved in glioblastoma multiforme, the most malignant form of brain cancer." (PMID 29084609, 2017). "MSI1 overexpression has been observed in several tumor tissues, including glioblastoma (GBM), and is considered as a well-established marker for tumor metastasis and recurrence." (PMID 28821879, 2017). "Increasing evidence indicated that MSI1 promotes malignancy in hepatocellular carcinoma, lung cancer, cervical cancer or glioblastoma (GBM), by regulating proliferation, survival and tumorigenesis." (PMID 28821879, 2017). "Our findings are consistent with a previous study that discovered miR-137 as a negative regulator of MSI1 in a glioblastoma cell model." (PMID 25940441, 2015). "Recently, miRNAs negatively regulating MSI1 mRNA were identified and found to be dysregulated in glioblastoma." (PMID 25940441, 2015). "The post-transcriptional downregulation of m-Numb protein expression by canonical Msi1-Numb-Notch axis regulation has been found in wild type cerebral tissue, glioblastoma U251MG, leukemia cells and fibroblast NIH3T3 cells." (PMID 23308249, 2013). "Recent studies have shown that Notch and PI3K/Akt signaling pathways interact directly with Msi1 in glioblastoma, and that the interaction promotes cell growth." (PMID 23418578, 2013). "Among these, the RNA-binding protein Musashi1 (MSI1) has been identified as a candidate marker of cancer stem cells for glioblastoma." (PMID 22428049, 2012). "In this study, using an in vitro approach, we showed that MSI1 is highly expressed in various glioblastoma cell lines." (PMID 22428049, 2012). "MSI1-KD probably leads the glioblastoma cells to mitotic catastrophe, resulting in cell death by the accumulation of Numb protein and subsequent inhibition of the Notch signaling pathway." (PMID 22428049, 2012). "In the present study, to gain insight into the mechanism by which MSI1 contributes to tumor-cell generation or maintenance, we analyzed MSI1's functions in malignant glioblastoma." (PMID 22428049, 2012). "Collectively, these results suggested that the MSI1-KD-induced reduction in colony-forming cells in the glioblastoma cell line occurs through cell death, but via a pathway other than apoptosis, possibly necrosis." (PMID 22428049, 2012). "Immunoblot analysis revealed that MSI1-KD in glioblastoma cells resulted in the accumulation of Cyclin B1 due to prolongation of the M-phase." (PMID 22428049, 2012). "These previous reports and our current findings showed that MSI1-KD reduces tumor-cell survival and tumor-xenograft growth, and support its possible identification as a novel target for glioblastoma therapy." (PMID 22428049, 2012). "Immunocytochemical staining of the MSI1-KD glioblastoma cells indicated that they ectopically expressed metaphase markers." (PMID 22428049, 2012). "Our results suggest that a drug combination strategy (Msi1 + cell cycle/DNA replication inhibitors) could be a viable route to treat glioblastoma." (PMID 33804958, 2021). "The compound diminished MSI1′s positive impact on the expression of pro–oncogenic target genes and reduced proliferation, cell viability, colony formation, migration and invasion of glioblastoma cells." (PMID 34062997, 2021). "Importantly, glioblastoma cells with Msi1 KO showed increased sensitivity to cell cycle and DNA replication inhibitors." (PMID 33804958, 2021). "Moreover, it is worth noting that Msi1 was found to positively regulate YTHDF1 expression in glioblastoma." (PMID 34916907, 2021). "Therefore, the MSI1/miR-671-5p/STAT3 axis enhances radioresistance, and the MSI1/miR-671-5p/TRAF2 axis activates glioblastoma stem cell-like properties and EMT-like abilities." (PMID 35052701, 2021). "In glioblastoma Msi1 KO cells, we observed increased p21 and p27 expression." (PMID 33804958, 2021). "Regulation of DNA replication was identified as a new core function of Msi1 in glioblastoma cells." (PMID 33804958, 2021).
glioblastoma (continued). "Similarly, we showed that the regulation of cell cycle and division is the main route for Msi1 of contribution to glioblastoma development." (PMID 35011618, 2021). "Besides breast cancer, MSI-1 is also prognostically relevant for other tumor entities, including colon cancer and glioblastoma." (PMID 34291358, 2021). "Interestingly, we determined that Msi1 KO cells are more sensitive to Triapine and Olaparib and a synergistic effect was observed when we treated glioblastoma cells with Olaparib and Luteolin, a Msi1 inhibitor." (PMID 33804958, 2021). "Based on our results indicating that Msi1 KO cells are more sensitive to cell cycle and DNA replication inhibitors, other agents in combination with Msi1 inhibitor could be explored to treat glioblastoma." (PMID 33804958, 2021). "Moreover, glioblastoma lines with Msi1 knockout (KO) displayed increased sensitivity to cell cycle and DNA replication inhibitors." (PMID 33804958, 2021). "Recent study about molecular mechanisms of the cell migration in glioblastoma indicated that MSI1 promotes cell migration by inhibition in translation of Tensin3, a negative regulator of migration, and overexpression of Intercellular Adhesion Molecule-1 (ICAM1)." (PMID 32448364, 2020). "Therefore, in glioblastoma, MSI1 has a major role in migration, adhesion, and invasion pathways by interacting with target genes." (PMID 32448364, 2020). "In addition, RBP Musashi1 (MSI1) is restrained by a class of tumor suppressor miRNAs, including miR-34a, miR-101, miR-128, miR-137, and miR-138, and this inhibition reduces glioblastoma progression." (PMID 32653017, 2020). "In glioblastoma and medulloblastoma cells, the downregulation of MSI1 induced elongation of mitosis by accumulation of cyclin B1 in addition to the reduction of notch and PI3 kinase-Akt signaling pathways which results in reduction of the cell growth and survival." (PMID 32448364, 2020). "However, in our glioblastoma cells, Cyclin B1 was probably appropriately down-regulated by MSI1 through an indirect or direct pathway." (PMID 22428049, 2012). "We further showed that MSI1-KD glioblastoma cells xenografted into the brains of NOD/SCID mice formed tumors that were 96.6% smaller, as measured by a bioluminescence imaging system (BLI), than non-KD cells, and the host survival was longer (49.3±6.1 days vs. 33.6±3.6 days; P<0.01)." (PMID 22428049, 2012). "Furthermore, in glioblastoma cells, we found that MSI1-KD led to decreased Notch signaling activity, as represented by the level of cleaved Notch, and to the accumulation of Numb." (PMID 22428049, 2012). "Therefore, MSI1-KD probably leads the glioblastoma cells to undergo mitotic catastrophe, resulting in cell death caused by the accumulations of Numb and Cyclin B1 proteins and by the inhibition of Notch." (PMID 22428049, 2012). "MSI1 could promote tumor progression through interaction with Ago2 in glioblastoma." (PMID 32448364, 2020). "Thus, Msi1 expression in lung cancer cells has similar characteristics and function as previously noted for breast cancer, medulloblastoma, glioblastoma and colon cancer cells, and is consistent with the original observation of Msi1 being a marker for neural stem and progenitor cells." (PMID 23715514, 2013). "YTHDF1 is elevated in glioblastoma (GBM) and positively regulated by MSI1 whereas both of these proteins are related to worse prognosis in glioblastoma patients." (PMID 36650570, 2023). "Previous studies have shown that Msi1 can activate AKT signaling in lung cancer and glioblastoma to promote malignancy 22,23." (PMID 33758618, 2021). "We established that Msi1 levels affect the expression of Bub1, Bub1B, MADL1 and CDC20 and Bub3 is a direct target of Msi1 in glioblastoma cells." (PMID 33804958, 2021).